COMT (catechol-O-methyltransferase)
Diseases named in the same sentence as COMT in open-access papers (continued):
Sharing a sentence is not in itself a finding about the gene and the disease.
autism (6 papers, 2013 to 2024). Persistent deficits in social interaction and communication and interaction as well as a markedly restricted repertoire of activity and interest as well as repetitive patterns of behavior. "While three autism patients have homozygous (rs4633-TT and rs4680- AA) genotypes in both the COMT variants (rs4633 and rs4680), one autism patient has heterozygous (rs4633-CT and rs4680-AG) genotypes in both variants." (PMID 39148948, 2024). "Strikingly, four additional genes present in the same linkage blocks affect social abilities in humans, e.g., SEZ6L has been associated with autism and COMT affects aggression in adolescents with ADHD." (PMID 27685260, 2016). "COMT, one of the autism susceptibility genes in this chromosomal region has also been investigated in correlation with language production and semantic verbal fluency." (PMID 23840741, 2013). "Therefore, overt-autism would be:caused by the persistence of epigenetic regulations (MAOA-, COMT +) after the end of a prenatal monoaminergic disruption (excess MAOA)." (PMID 30558545, 2018).
autism spectrum disorder (6 papers, 2017 to 2025). A spectrum of developmental disorders that includes autism, and Asperger syndrome. "For autism spectrum disorder, DGCR2, ARVCF, GNB1L, COMT, ZDHHC8, CHRNA7, and NRXN1 are candidate genes with various associated developmental defects." (PMID 37486921, 2023).
Borderline personality disorder (6 papers, 2012 to 2025). A personality disorder characterized by impulsive behavior and unpredictable, capricious mood. "A substantial literature has examined COMT polymorphisms in the context of borderline personality disorder (BPD)." (PMID 41440133, 2025). "Furthermore we found that the well-known hypoalgesia in borderline personality disorder for thermal pain is not simply explained by the COMT val158met polymorphism." (PMID 22247753, 2012).
brain tumor (6 papers, 2016 to 2023). "COMT has been investigated in childhood brain tumor survivors, where Met/Val heterozygotes outperform Met/Met and Val/Val homozygotes (rs4680; Val158Met)." (PMID 35814456, 2022).
colorectal cancer (6 papers, 2021 to 2025). A primary or metastatic malignant neoplasm that affects the colon or rectum. "We examined whether a COMT gene variant modulates the effect of dietary vitamin E intake on colorectal cancer (CRC) risk." (PMID 37974041, 2023). "In this follow-up research, we observed the interaction of these gene polymorphisms (COMT, GSTM1, GSTT1, MGMT, NQO1, and XRCC1) with different meat diets and on outcomes linked to colorectal cancer risk: ATNC levels, DNA adduct levels, and DNA strand breaks." (PMID 38337709, 2024). "Other studies showed COMT overexpression in colorectal cancer, and glioma." (PMID 40490448, 2025). "COMT overexpression can decrease cell proliferation and invasion in colorectal cancer." (PMID 34209963, 2021).
endometrial cancer (6 papers, 2011 to 2021). Primary or metastatic malignant neoplasm involving the endometrium (mucous membrane that lines the endometrial cavity). "In support of this, studies have linked mutations in COMT with an increased risk of endometrial cancer and premature ovarian insufficiency in humans." (PMID 31718557, 2019). "In this study, COMT expression was significantly decreased in endometrial cancer, both at the gene and protein levels." (PMID 34768458, 2021). "Methylation of the COMT gene can inactivate COMT and may result in the carcinogenesis of endometrial cancer." (PMID 34209963, 2021). "The analysis showed that as the grade of endometrial cancer increased, DRD5 and COMT levels decreased significantly." (PMID 34768458, 2021). "It has been observed that as endometrial cancer progresses, expression of CXCL12, GNAL, OPRK1, DRD2, and DRD3 increases while DRD5 and COMT levels are gradually reduced." (PMID 34768458, 2021). "Expression of CXCL12, OPRK1, DRD5, COMT, DRD2, and DRD3 proteins was assessed in the serum of endometrial cancer patients and control group using ELISA." (PMID 34768458, 2021). "It has been observed that miRNAs differentiating endometrial cancer from control are probably not involved in the reduction in COMT expression." (PMID 34768458, 2021). "Microarray analysis showed that DRD2 was overexpressed regardless of endometrial cancer grade, while COMT and DRD5 showed a significant decrease in expression." (PMID 34768458, 2021). "In addition, the COMT gene differentiated endometrial cancer samples from the control regardless of its grade, which indicates its potential utility as a complementary marker in endometrial cancer diagnostics." (PMID 34768458, 2021).
heroin dependence (6 papers, 2011 to 2024). Physical and psychological dependence on the drug heroin. "Our study identified variations in five candidate genes, including GRIN3A, GRIN3B, CYP2C19, TPH2, and COMT, contributing to susceptibility to heroin addiction." (PMID 33915886, 2021). "Our findings indicate that the COMT gene is associated with urge for heroin, which plays a critical role in heroin dependence." (PMID 33915886, 2021). "Our previous work indicated that the COMT gene SNP rs737866 was associated with heroin dependence." (PMID 23155402, 2012). "In one of the subjects genotyped with heroin addiction, carries of the DRD2 A1 allele, also carried the low enzyme COMT activity genotype (A/A)." (PMID 24878765, 2014). "The impact of environmental factor was greater than the COMT gene in the development of heroin dependence." (PMID 23155402, 2012). "Our findings indicated that the COMT gene, impulsive personality traits and childhood trauma experience were interacted to impact the age of onset of heroin use, which play a critical role in the development of heroin dependence." (PMID 23155402, 2012). "The respective influence of COMT gene, childhood trauma and impulsivity personality in the development of heroin dependence, is also unknown." (PMID 23155402, 2012). "Our results indicate that the COMT rs737866 TT genotype is related to higher NS scores and that individuals with higher NS scores have an earlier onset age of drug use-which would increase the likelihood and severity of subsequent heroin dependence." (PMID 21857968, 2011).
leiomyoma (6 papers, 2009 to 2023). A well-circumscribed benign smooth muscle neoplasm characterized by the presence of spindle cells with cigar-shaped nuclei, interlacing fascicles, and a whorled pattern. "The activity of the COMT enzyme is elevated in human leiomyoma tissue as compared with normal myometrium; since this enzyme is essential for estrogen metabolism, the observed association suggests a possible causal role of COMT in UL formation." (PMID 33552117, 2020). "Catechol-O-methyl transferase (COMT) is an enzyme expressed at a higher level in leiomyoma as compared to the normal myometrium." (PMID 35800452, 2022). "In vitro study showed that the ability of green tea extract in inhibiting the proliferation of leiomyoma cells is in part due to the potential of EGCG in reducing the expression of the COMT enzyme." (PMID 35800452, 2022). "Moreover, COMT has been shown to have much higher expression in leiomyomas compared to normal myometrium." (PMID 36986169, 2023). "Furthermore, treatment with EGCG modulated survival and stress signaling pathways in wild-type leiomyoma cells, but these effects were minimal or reversed in COMT-silenced leiomyoma cells." (PMID 36986169, 2023). "Interestingly, one study has demonstrated that EGCG inhibits COMT activity and protein expression in human leiomyoma cells in vitro." (PMID 36986169, 2023). "Hence, further study is warranted to confirm the antiproliferative effect of EGCG on leiomyoma via the COMT pathway." (PMID 35800452, 2022). "In this study, we tested the hypothesis that 2ME or COMT gene over expression, by the virtue of 2ME formation, inhibit the proliferation of human leiomyoma cells by affecting MT dynamic which in turn regulate the nuclear receptors signaling pathways." (PMID 19809499, 2009). "We have further examined whether manipulation of COMT expression, by the virtue of 2ME formation, can affect leiomyoma cells." (PMID 19809499, 2009). "Thus, COMT/2ME-induced microtubule stabilization leads to cytoplasmic retention and nuclear compartmentalization impairment of ERα and PRs, and consequently leiomyoma cells growth arrest." (PMID 19809499, 2009). "The ability of COMT/2ME to reduce basal (i.e. unstimulated) CYP19 expression may result from blocking the autocrine/paracrine actions of cytokines and PGE2, which are known inducers of CYP19 in leiomyomas cells." (PMID 19809499, 2009).
temporomandibular joint disorder (6 papers, 2015 to 2025). Any condition affecting the anatomic and functional characteristics of the temporomandibular joint. "For example, an A to G synonymous SNP at a Leu codon, present in the coding region of the catechol-O-methyltransferase (COMT) mRNA, was identified in subjects with high pain sensitivity and at greater risk of developing temporomandibular joint disorder." (PMID 30425729, 2018). "COMT regulates pain perception and there are three haplotypes of the COMT gene that are associated with pain perception and developing temporomandibular joint disorder." (PMID 28536625, 2016). "The COMT, HTR2A, MMPs, IL-1β, IL-6, TNF-α and ESR1 are known to influence the pain perception, inflammation, and joint integrity in temporomandibular joint disorders." (PMID 40291793, 2025).
type 2 diabetes (6 papers, 2008 to 2020). "COMT rs4680 high-activity G-allele was found to associate with a lower HgbA1c level and protection from type II diabetes." (PMID 32498358, 2020). "This study showed that the presence of one or two A allele of the COMT Val108/158Met was associated with improved glycemic response, and with a better response to insulin detemir therapy in patients with type II diabetes, separating them as best candidates for detemir therapy." (PMID 29225702, 2017). "Moreover, a low-activity variant of COMT (val/met 158) may contribute to MS, whereas the high-activity form of COMT (rs4680) is associated with lower HbA1c and protection from type 2 diabetes." (PMID 31877978, 2019). "Analyses of impaired glucose tolerance (IGT) and type 2 diabetes (T2D) revealed, a 12.3% increased frequency of 5HT2C rs3813929 T-allele and an 11.6% increased frequency of COMT rs4680 GG-genotype in individuals with IGT or T2D (χ2, p = 0.05 and p = 0.06, respectively)." (PMID 19690620, 2009).
bruxism (5 papers, 2014 to 2025). Excessive clenching of the jaw and grinding of the teeth. "Variations in genes like 5HTR2A, DRD2, DRD3, ANKK1, COMT, MMP9, ACTN3, and ANKK1 are linked with the susceptibility to Bruxism." (PMID 40291793, 2025). "SNP in the DRD2 gene was associated with bruxism and its circadian phenotype, whereas SNPs in ANKK1 and COMT were found to be associated with circadian phenotypes of bruxism." (PMID 37252006, 2023). "In adults, there is also a correlation between bruxism and COMT, and orthodontic treatment is also related to it, but there is no relevant experimental evidence that directly prove the therapeutic effect of COMT on orthodontic tooth movement." (PMID 34725639, 2021).
chronic fatigue syndrome (5 papers, 2015 to 2024). "Chronic fatigue syndrome (CFS) is a heterogeneous disorder with a genetically associated vulnerability of the catecholamine metabolism (e.g., catechol O-methyltransferase polymorphisms), in which environmental factors have an important impact." (PMID 39063020, 2024).
degenerative disc disease (5 papers, 2012 to 2022). "For example, the COMT haplotype rs4680 G, rs6269 A, rs4633 C, rs4818 C is associated with slower recovery after surgical treatment for lumbar degenerative disc disease." (PMID 27964712, 2016). "In addition, human disc degeneration is linked to a new catechol-O-methyltransferase (COMT) variation." (PMID 36009290, 2022). "The observed associations suggest that it seems unlikely that treatment responses can be predicted solely by the analysis of COMT gene polymorphisms and it may be recommended to assess the influence of candidate genes for both disc degeneration and pain in a larger cohort." (PMID 22612913, 2012). "In addition, COMT haplotype was associated with less chronic postoperative pain (greater improvement in Oswestry Disability Index scores) in patients with disk degenerative disease one year after surgery, suggesting that COMT variation may be predictive in terms of treatment outcome." (PMID 24278778, 2013).
delirium (5 papers, 2020 to 2026). A disorder characterized by confusion; inattentiveness; disorientation; illusions; hallucinations; agitation; and in some instances autonomic nervous system overactivity. "Moreover, candidate gene association studies on delirium have shown that apolipoprotein E, catechol-O-methyltransferase (COMT), and dopamine-signaling genes such as dopamine receptor 2 are related to the risk of delirium." (PMID 33086708, 2020). "COMT, MYD88, and CYP1B1 were identified as key candidate genes underlying opioid-associated delirium." (PMID 42307217, 2026). "The association between the postoperative plasma concentration of CRP and the incidence, duration, and severity of postoperative delirium can be modified by the apolipoprotein E (APOE) 4 genotype and the catechol-O-methyltransferase (COMT) genotype." (PMID 36212043, 2022).
emotional dysregulation (5 papers, 2017 to 2022). "Since one of the main characteristics of self-injurers is emotional dysregulation, we could propose that the COMT gene polymorphism might also play a role in NSSI engagement." (PMID 33807669, 2021). "The decreased COMT enzyme activity results in higher cortical dopamine levels, and therefore inflexible processing of affective stimuli, which is a mechanism that possibly accounts for emotional dysregulation." (PMID 33807669, 2021). "The goal of this study was to explore the moderating role of a polygenic dopamine composite consisting of COMT and DRD2 in the relationship between peer victimization and externalizing problems in Chinese adolescents, as mediated by emotion dysregulation, and the potential sex differences." (PMID 36397091, 2022).
glioma (5 papers, 2021 to 2025). A benign or malignant brain and spinal cord tumor that arises from glial cells (astrocytes, oligodendrocytes, ependymal cells). "COMT inhibition leads to mitochondrial dysfunction in glioma cells, activating the cellular antiviral double-stranded RNA sensing pathway and the type I interferon response to enhance the efficacy of radiotherapy." (PMID 40299330, 2025). "A recent study discovered that upregulation of HTR2A, which is a target in inflammatory mediator regulation of Transient Receptor Potential (TRP) channels, and COMT was significantly positively correlated with glioma carcinogenesis." (PMID 38003496, 2023). "Studies have shown that COMT inhibition may be a promising approach to enhance glioma radiotherapy through a novel immune mechanism." (PMID 40299330, 2025). "In this last study, COMT inhibition led to sensitization of glioblastoma cells to radiotherapy by impairing mitochondria homeostasis, strongly supporting its targeting to treat glioma." (PMID 40490448, 2025). "The prognosis for glioma patient survival may be further impacted by the expression of HTR2A and COMT, which could further impact the effectiveness of immunotherapy." (PMID 38003496, 2023).
lung carcinoma (5 papers, 2012 to 2021). "XRCC1 and COMT gene polymorphisms and COFs exposure are central risk factors in the progression of lung cancer." (PMID 34837917, 2021). "Five publications, including six individual studies with a total of 4,043 subjects (1,796 cases and 2,247 controls) regarding the association of COMT Val158Met polymorphism with lung cancer susceptibility were included in this meta-analysis." (PMID 25280560, 2014). "So far, no meta-analysis had been conducted to investigate the association between COMT Val158Met polymorphism and Lung cancer." (PMID 25280560, 2014). "Several epidemiologic studies have reported the role of COMT Val158Met polymorphism in the risk of lung cancer." (PMID 25280560, 2014). "Although only limited studies were included, our meta-analysis provided a new evidence of the null association between COMT Val158Met polymorphism and overall lung cancer risk." (PMID 25280560, 2014). "Firstly, there were only a few studies investigating relationship between COMT polymorphisms and lung cancer risk, therefore, the sample size of our meta-analysis was relatively small." (PMID 25280560, 2014). "Although we took considerable efforts to collect all available data to investigate the association of COMT Vall58Met polymorphism and its correlation with lung cancer risk, there were also some limitations to be addressed." (PMID 25280560, 2014). "Up to date, a number of molecular epidemiologic case–control studies have shown the potential role of COMT Val158Met polymorphism in the risk of lung cancer." (PMID 25280560, 2014). "Therefore, five publications, consisting of six individual studies with a total of 4,043 subjects (1,796 cases, 2,247 controls) regarding association of COMT Val158Met polymorphism with lung cancer risk were included in this meta-analysis." (PMID 25280560, 2014). "Therefore, the meta-analysis was performed to provide a quality reevaluation of the association between the COMT Val158Met polymorphism and the risk of lung cancer." (PMID 25280560, 2014). "This SNP in the COMT gene has been associated with an increased risk of lung cancer." (PMID 23162467, 2012). "However, a borderline significant association indicated that COMT Vall58Met polymorphism might increase lung cancer susceptibility." (PMID 25280560, 2014). "The association between the Val158Met polymorphism in the catechol-O-methyltransferase (COMT) gene and lung cancer risk remains controversial and inconclusive." (PMID 25280560, 2014). "As COMT can act as a detoxication enzyme for PAH catechols, it is possible that these polymorphic variants may increase susceptibility to lung cancer caused by PAH." (PMID 23162467, 2012). "COMT polymorphism is associated with the risk of lung cancer in non-smoking women." (PMID 34209963, 2021). "Furthermore, COMT Vall58Met polymorphism appeared to have no influence on the risk of lung cancer either, when studies were stratified by ethnicity, source of controls and smoking status." (PMID 25280560, 2014).